PIAS3 (protein inhibitor of activated STAT 3)
Description:
Functions as an E3-type small ubiquitin-like modifier (SUMO) ligase, stabilizing the interaction between UBE2I and the substrate, and as a SUMO-tethering factor. Plays a crucial role as a transcriptional coregulation in various cellular pathways, including the STAT pathway and the steroid hormone signaling pathway. Involved in regulating STAT3 signaling via inhibiting STAT3 DNA-binding and suppressing cell growth. Enhances the sumoylation of MTA1 and may participate in its paralog-selective sumoylation. Sumoylates CCAR2 which promotes its interaction with SIRT1. Diminishes the sumoylation of ZFHX3 by preventing the colocalization of ZFHX3 with SUMO1 in the nucleus.
Synonyms: FLJ14651; ZMIZ5
Tractability: PROTAC: UniProt records ubiquitination sites on it; ubiquitination databases record sites on it.
Gene: Protein-coding gene on chromosome 1 (145,848,521 to 145,859,836, reverse strand). Ensembl gene ENSG00000131788.
Subcellular location: Cytoplasm; Nucleus; Nucleus speckle
Subcellular location (Human Protein Atlas): Nucleoplasm
Pathways (Reactome):
Metabolism of proteins: SUMOylation of DNA replication proteins; SUMOylation of immune response proteins; SUMOylation of intracellular receptors; SUMOylation of transcription cofactors; SUMOylation of transcription factors
DNA Repair: Formation of Incision Complex in GG-NER
Gene Ontology:
Molecular function: protein binding; SUMO transferase activity; SUMO ligase activity; transcription coregulator activity; transcription regulator inhibitor activity; zinc ion binding
Biological process: negative regulation of protein sumoylation; positive regulation of protein sumoylation; negative regulation of receptor signaling pathway via JAK-STAT; negative regulation of transcription by RNA polymerase II; protein sumoylation
Cellular component: nucleoplasm; chromatin; cytoplasm; nuclear speck; nucleus; glutamatergic synapse; postsynaptic cytosol; presynaptic cytosol
Genetic constraint (gnomAD): Loss-of-function variants: 34 observed, 64.43 expected, observed/expected ratio (o/e) 0.53, 90% interval 0.4 to 0.7. The upper end of that interval is the gene's LOEUF score, 0.7, which puts it in group 2 of 6, group 1 being the genes least tolerant of losing a copy. Missense variants: 685 observed, 801.13 expected, observed/expected ratio (o/e) 0.86, 90% interval 0.8 to 0.91. Synonymous variants: 339 observed, 317.23 expected, observed/expected ratio (o/e) 1.07, 90% interval 0.98 to 1.17.
Homologues: Orthologues: chimpanzee PIAS3 (99% identical), pig PIAS3 (98% identical), mouse Pias3 (97% identical), guinea pig PIAS3 (96% identical), rat Pias3 (96% identical), dog PIAS3 (90% identical), rabbit PIAS3 (75% identical), tropical clawed frog pias3 (72% identical), Drosophila melanogaster Su(var)2-10 (37% identical). Paralogues in human: PIAS1 (60% identical), PIAS2 (54% identical), PIAS4 (38% identical), ZMIZ2 (23% identical), ZMIZ1 (21% identical).
Diseases named in the same sentence as PIAS3 in open-access papers:
PIAS3 is named in the same sentence as 74 diseases in open-access papers, as found by Europe PMC text mining. Sharing a sentence is not in itself a finding about the gene and the disease. The quoted sentences say what the papers report.
breast carcinoma (19 papers, 2013 to 2025). "Therefore, PIAS3 mimetics are promising candidates for the development of sensitizers for the treatment of BRCA-deficient breast cancers using DNA-damaging chemotherapeutic drugs and radiation." (PMID 24137461, 2013). "PIAS family members were differentially expressed in breast cancer, as PIAe S2 and PIAS3 were downregulated, whereas PIAS4 has a contradictory trend." (PMID 38590645, 2024). "We also found that PIAS3 played a deleterious prognostic factor in colorectal cancer (OS, DSS, DFS), while PIAS4 was a risk factor for breast cancer (DFS, RFS), lung cancer (OS) and brain cancer (OS)." (PMID 38528630, 2024). "Contrastingly, SUMO E3 ligase PIAS3-Smurf2 SUMOylation pathway represses the breast cancer cell-derived organoids." (PMID 38590645, 2024). "Collectively, these findings identify a novel role for PIAS3-mediated Smurf2 SUMOylation in the suppression of breast cancer cell invasion." (PMID 33968766, 2021). "Mechanistic studies showed that the SUMO E3 ligase PIAS3 maintains breast cancer organoids through Smurf2 SUMOylation under noninvasive conditions." (PMID 33968766, 2021). "The prognostic value of a single SUMO machinery component can also vary between cancer (sub)types, and, e.g., the value for PC2 and PIAS4 as prognostic biomarkers in breast cancer and for PIAS3 in mesothelioma remains ambiguous." (PMID 34503213, 2021). "Oncogenic miRNA-9 and miRNA-181a inhibit PIAS3 in IL-6high breast cancer to promote expansion of early-stage myeloid-derived suppressor cells, resulting in suppression of T-cell immunity." (PMID 34503213, 2021). "To date, PIAS3 expression has been found to be reduced in multiple malignancies, including gastric cancer, glioblastoma, ovarian cancer, and breast cancer." (PMID 30259640, 2018). "In a recent study, it was found that PIAS3 acts at least in part via SUMOylation of Smurf2 to suppress the invasive growth of breast cancer cell-derived organoids suggesting a potential anti-metastatic activity of SUMOylated-Smurf2." (PMID 30096838, 2018). "Early studies in glioblastoma multiforme (GBM) and breast cancer have indicated that in tumor cells derived from these cancers, PIAS3 expression is suppressed by proteasomal degradation." (PMID 30259640, 2018). "Future studies investigating the relevance of PIAS3-Smurf2 sumoylation pathway in breast cancer invasion and metastasis will help uncover novel biomarkers and therapeutic targets for breast cancer." (PMID 28423498, 2017). "In mechanistic studies, PIAS3 maintains breast cancer organoids in a non-invasive state via sumoylation of Smurf2." (PMID 28423498, 2017). "We next determined the relationship between PIAS3 and Smurf2 in the control of the malignant behavior of breast cancer cells." (PMID 28423498, 2017). "Mechanistically, our data suggest that PIAS3 acts via sumoylation of Smurf2 to suppress the invasive growth of breast cancer cells." (PMID 28423498, 2017). "In this study, we report our discovery that the PIAS3-Smurf2 sumoylation pathway suppresses the invasiveness of breast cancer cell-derived organoids." (PMID 28423498, 2017). "Together, these findings suggest that endogenous PIAS3 suppresses the aggressive behavior of breast cancer-derived organoids in a SUMO E3 ligase-dependent manner." (PMID 28423498, 2017). "Together, these data suggest that PIAS3 acts via sumoylation of Smurf2 to inhibit the invasive behavior of breast cancer cell-derived organoids." (PMID 28423498, 2017). "In conclusion, our findings demonstrate that the PIAS3-Smurf2 sumoylation pathway suppresses the invasive behavior of breast cancer cell-derived organoids." (PMID 28423498, 2017). "We also find that the SUMO E3 ligase PIAS3 inhibits the invasive growth of breast cancer cell-derived organoids." (PMID 28423498, 2017). "Collectively, our findings define a novel role for the PIAS3-Smurf2 sumoylation pathway in the suppression of breast cancer cell invasiveness." (PMID 28423498, 2017).
breast carcinoma (continued). "XTT, immunoblotting, and chromatin immunoprecipitation (Chip) were used to examine the biological effect of PIAS3 in breast cancer cells." (PMID 26768588, 2016). "To determine the prognostic significance of PIAS3 in patients with breast cancer, we first used immunoblotting to analyze the expression patterns in paired cancerous and adjacent noncancerous breast tissues from the same patient." (PMID 26768588, 2016). "To determine the potential roles of PIAS3 in breast cancer regarding ER status, we transiently introduced the PIAS3 expression plasmid into ER-positive MCF-7 and T47D cells as well as ER-negative MDA-MB-231 and SKBR3 cells." (PMID 26768588, 2016). "In addition, PIAS3 is upregulated in lung cancer, breast cancer, prostate cancer, colorectal cancer, and brain tumors." (PMID 33898460, 2021). "The E3 enzyme PIAS3 was overexpressed in prostate, lung, colon, brain and breast cancers." (PMID 33968766, 2021). "The role of PIAS3 in breast cancer remains to be elucidated." (PMID 28423498, 2017). "Our data support the idea that reduction in the abundance of PIAS3 might be important for the invasive behavior of breast cancer cell-derived organoids." (PMID 28423498, 2017). "Quantitative analyses of the proportion of MDA-MB-231 breast cancer cell-derived organoids showing an invasive behavior revealed that expression of PIAS3 shRNA-1 and PIAS3 shRNA-2 alone or together led to 65% increase in the number of breast cancer cell-derived organoids with invasive growth." (PMID 28423498, 2017). "It will be interesting to probe whether the protein abundance or activity of PIAS3 might be altered in breast cancer." (PMID 28423498, 2017). "Deregulated STAT3 signaling has been associated with breast cancer and thus, alterations in PIAS3 may also play a role in breast cancer." (PMID 26768588, 2016). "In the present study, we explored whether the expression of total PIAS3 protein was aberrantly expressed and whether these alterations contributed to breast cancer progression." (PMID 26768588, 2016). "Our results revealed that PIAS3 may be a biomarker for predicting hormone therapy stratification in patients with breast cancer." (PMID 26768588, 2016). "This suggests that other co-regulators (i.e., ER) may change the functions and activities of PIAS3 at least in breast cancer." (PMID 26768588, 2016). "In addition, as seen during clinical observations and in vitro studies, increased PIAS3 may attenuate the therapeutic effects of Tam-based hormone therapy in breast cancer patients as well as the cytotoxicity of Tam to the breast cancer cells." (PMID 26768588, 2016). "Our results suggest that PIAS3 may play a role in breast cancer, along with ER." (PMID 26768588, 2016). "Identifying key signaling pathways and regulatory molecules, such as PIAS3, PIP, STAT5, and SOCS3 in breast cancer (BC) cells, can provide valuable insights into the mechanisms of the disease and potentially lead to the development of targeted therapies." (PMID 40003884, 2025). "MiRNA-9 and miRNA-181a found in breast cancer sEVs promote the expansion of MDSCs through their targets suppressor of cytokine signalling 3 (SOCS3) and protein inhibitor of activated STAT protein 3 (PIAS3)." (PMID 36096820, 2022). "Moreover, SNP variant rs17354559 of PIAS3 may be of functional relevance in breast cancer, although the variant was not evaluated experimentally." (PMID 34503213, 2021). "Thus, inhibition of PIAS3 may be an attractive therapeutic target in HR-positive breast cancer, but although the targeting of PIAS1 in breast cancers overexpressing PIAS1 could potentially relieve PIAS1-mediated epigenetic repression, the role of PIAS1 as a repressor of invasion must be considered." (PMID 34503213, 2021).
breast carcinoma (continued). "However, the expression levels of cyclin D1 and c-myc, but not those of Bcl-2 and Mcl-1, were increased upon PIAS3 overexpression in MCF7 cells, suggesting that the PIAS3-mediated effects on ER-positive breast cancer cells may be promoter-specific or ER-related." (PMID 26768588, 2016). "Our previous work demonstrated that tumor exosomal miR-9 (targeting SOCS3) and miR-181a (targeting PIAS3) synergistically activate the JAK/STAT signaling pathway, driving MDSC expansion and suggesting novel intervention strategies for IL-6-driven breast cancer." (PMID 41281644, 2025). "Samples from 25 breast cancer patients and non-cancerous tissues from the same breast were obtained and PIAS3 mRNA and quantified." (PMID 38590645, 2024). "Tumor exosome-derived miR-9 and miR-181a activate the JAK/STAT pathway by targeting the PIAS3 and SOCS3, thus promoting the expression of eMDSCs and might be providing as novel target for IL-6high breast cancer treatment." (PMID 38590645, 2024). "Total PIAS3 protein decreased in 62 % of the 100 breast cancer tissues compared with that in the adjacent noncancerous tissues." (PMID 26768588, 2016). "PIAS3 mRNA expression was considerably lower in these patients as compared to non-cancerous tissues; thus, PIAS3 mRNA might be crucial in breast cancer development." (PMID 38590645, 2024). "Remarkably, expression of the SUMO E3 ligase inactive PIAS3CS, in which the RING finger Cysteine 299 is converted to serine, promoted the invasive growth of breast cancer cell-derived organoids even in the absence of TGFβ phenocopying the effect of PIAS3 knockdown." (PMID 28423498, 2017). "Although the correlations did not achieve significance, we found that decreased PIAS3 expression may contribute to advanced breast cancer development including the advanced tumor staging and positive node metastasis observed in our cases." (PMID 26768588, 2016). "Meanwhile, PIAS3 increased cyclin D1 expression in MCF-7 and T47D cells but inhibited the same in MDA-MB-231 and SKBR3 cells, suggesting that different effects of PIAS3 on breast cancer cells may be modulated by ER." (PMID 26768588, 2016). "Our results showed that the total PIAS3 level was mainly lower in the breast cancer tissues than in the adjacent noncancerous tissues, suggesting that a reduction of PIAS3 levels in native breast tissues may be associated with breast cancer development." (PMID 26768588, 2016). "Therefore, it is important to understand the clinical significance and underlying mechanisms of its downstream, negative feedback regulator, PIAS3, in breast cancer." (PMID 26768588, 2016). "Also, PIAS3 overexpression has been shown to inhibit cell growth and increase drug sensitivity in lung cancer, and several studies have indicated that COX2 inhibitors (NSAIDs and celecoxib) have protective effects against colorectal cancers and breast cancers." (PMID 24550933, 2014).
glioblastoma (15 papers, 2011 to 2025). The most malignant astrocytic tumor (WHO grade IV). "PIAS3 is also implicated in the regulation of stem-like properties of glioblastoma (GBM) cells." (PMID 35887358, 2022). "In fact, studies have demonstrated that PIAS3 expression is reduced in various cancers, such as malignant melanoma, glioblastoma, lung squamous cell carcinoma, and anaplastic lymphoma." (PMID 39335615, 2024). "On the other hand, the upregulation of PIAS3 expression in various tumors can inhibit cell proliferation and increase drug chemosensitivities such as lung cancer, prostate cancer, and glioblastoma." (PMID 39335615, 2024). "It is reported that reduced PIAS3 in glioblastoma tissues promotes tumor-cell proliferation, and PIAS3 overexpression inhibits glioblastoma-cell growth by reducing STAT3." (PMID 37298405, 2023). "Overexpression of PIAS3 reduces the STAT3 transcription in glioblastoma and ovarian cancer." (PMID 38590645, 2024). "Interestingly, studies have identified that inhibition of miR-125b enhanced the chemosensitivity of glioblastoma stem cells to temozolomide through regulating Bak1 (Bcl-2 antagonist killer 1) and PIAS3 (protein inhibitor of activated signal transducer and activator of transcription)." (PMID 25605244, 2015). "In glioblastoma, tri‐partite motif‐containing protein 8 (TRIM8) and nuclear-Smad6 arbitrate the ubiquitination that persuades degradation of PIAS3, which in turn promotes STAT3 activation." (PMID 38590645, 2024). "Proteasomal inhibitors bortezomib or marizomib induce caspase 9 and increase PIAS3 expressions that initiated apoptosis and inhibit STAT3 activity in glioblastoma cells." (PMID 38590645, 2024). "In the case of Smad6, MH2 domain and PIAS3 ring domain are responsible for their interaction that degrades PIAS3 and promotes STAT3 activity in glioblastoma." (PMID 38590645, 2024). "As can be seen from the figure, UBE2I, UBA2, PIAS3, and SENP1 were upregulated in glioblastoma, whereas PIAS1, RANBP2, SENP5, and SENP2 were downregulated in glioblastoma." (PMID 33898460, 2021). "UBE2I, UBA2, PIAS3, and SENP1 were highly expressed in glioblastoma." (PMID 33898460, 2021). "Moreover, UBE2I, UBA2, PIAS3, and SENP1 were highly expressed in glioblastoma, whereas PIAS1, RANBP2, SENP5, and SENP2 were downregulated in glioblastoma." (PMID 33898460, 2021). "LN-18 glioblastoma cells are insensitive to resveratrol due to the more inducible brain-associated SULT expression, insufficiency of resveratrol to suppress activated STAT3 signaling and the lack of PIAS3 nuclear translocation." (PMID 22096581, 2011). "It has been reported that TRIM8 cancels the negative effect of PIAS3 on STAT3 by degradation of PIAS3 and enhances Src-dependent tumorigenesis of glioblastoma." (PMID 38879600, 2024).